ZSCAN12 (zinc finger and SCAN domain containing 12)
Description:
May be involved in transcriptional regulation.
Synonyms: KIAA0426; ZNF305; ZNF96; ZNF29K1; ZFP96; dJ29K1.2
Tractability: PROTAC: UniProt records ubiquitination sites on it; ubiquitination databases record sites on it.
Gene: Protein-coding gene on chromosome 6 (28,378,821 to 28,399,747, reverse strand). Ensembl gene ENSG00000158691.
Subcellular location: Nucleus
Subcellular location (Human Protein Atlas): Nucleoplasm; Cytosol; Nuclear bodies
Gene Ontology:
Molecular function: protein binding; DNA-binding transcription factor activity, RNA polymerase II-specific; RNA polymerase II cis-regulatory region sequence-specific DNA binding
Biological process: regulation of transcription by RNA polymerase II
Cellular component: nucleus
Genetic constraint (gnomAD): Loss-of-function variants: 19 observed, 24.95 expected, observed/expected ratio (o/e) 0.76, 90% interval 0.53 to 1.12. The synonymous counts are far from expectation, so gnomAD's model fits this gene poorly and the ratio says little. Missense variants: 650 observed, 740.49 expected, observed/expected ratio (o/e) 0.88, 90% interval 0.82 to 0.94. Synonymous variants: 186 observed, 253.72 expected, observed/expected ratio (o/e) 0.73, 90% interval 0.65 to 0.83.
Homologues: Orthologues: chimpanzee ZSCAN12 (99% identical), macaque ZSCAN12 (97% identical), pig ZSCAN12 (82% identical), dog ZSCAN12 (79% identical), rabbit ZSCAN12 (75% identical), rat Zscan12 (57% identical), mouse Zscan12 (56% identical). Paralogues in human: ZKSCAN8 (41% identical), ZNF397 (40% identical), ZSCAN30 (39% identical), ZSCAN31 (37% identical), ZKSCAN3 (36% identical), ZKSCAN4 (36% identical), ZSCAN23 (35% identical), ZSCAN21 (35% identical), ZKSCAN1 (34% identical), ZSCAN26 (33% identical), ZNF394 (32% identical), ZSCAN22 (32% identical), and 18 more.
Diseases named in the same sentence as ZSCAN12 in open-access papers:
ZSCAN12 is named in the same sentence as 6 diseases in open-access papers, as found by Europe PMC text mining. Sharing a sentence is not in itself a finding about the gene and the disease. The quoted sentences say what the papers report.
endometrial cancer (6 papers, 2022 to 2025). Primary or metastatic malignant neoplasm involving the endometrium (mucous membrane that lines the endometrial cavity). "Another group from the United Kingdom (UK) analyzed cervicovaginal samples of 399 patients with ZSCAN12 and GYPC region methylation and found a sensitivity of 90.9% and specificity of 92.1% for endometrial cancer detection." (PMID 41008854, 2025). "We have recently developed and validated the WID‐qEC test, which assesses DNA methylation of ZSCAN12 and GYPC via real‐time PCR, to triage women with symptoms suggestive of endometrial cancer using ThinPrep‐based liquid cytology samples." (PMID 36056582, 2023). "We describe the Women's cancer risk IDentification – quantitative polymerase chain reaction test for Endometrial Cancer (WID-qEC), a three-marker test that evaluates DNA methylation in gene regions of GYPC and ZSCAN12." (PMID 36001862, 2022). "Utilizing cervical scrapings as a potential genetic material, coupled with the use of DNA hypermethylation in specific genes, including CDO1, CELF4, BHLHE22, POU4F3, MAGI2, CADM1, MAL, miR124-2, ZSCAN12, and GYPC, has been investigated for endometrial cancer detection." (PMID 41008854, 2025).
cancer (2 papers, 2022 to 2024). A tumor composed of atypical neoplastic, often pleomorphic cells that invade other tissues. "The WID-qEC test, based on ZSCAN12 and GYPC DNA methylation, appeared to be an excellent predictor of near-term (<1 year) EC risk (sensitivity: 91%; specificity: 100%), but not effective in assessing long-term (≥ 1 year) cancer risk (sensitivity: 20%)." (PMID 39902129, 2024).
tumor (2 papers, 2022 to 2023). "For a total of 471 cases of advanced GC, NCOR2, PARK2, and ZSCAN12 methylation statuses were determined in DNA samples obtained from tissue slides with representative tumor histology." (PMID 35039565, 2022). "For three methylation markers, NCOR2, PARK2, and ZSCAN12, correlation of their methylation levels with the densities of CD3+ or CD8+ cells at the tumor center or invasive front was found." (PMID 35039565, 2022). "Through genome-wide methylation profiling, NCOR2, PARK2, and ZSCAN12 were found to be highly methylated in CD3-positive and CD8-positive cells and rarely methylated in tumor cells." (PMID 35039565, 2022).
ZSCAN12 also shares sentences with these, for which no sentence is quoted: depression (1 paper); gastric cancer (1); prostate carcinoma (1).